IFNG (interferon gamma)
Diseases named in the same sentence as IFNG in open-access papers (continued):
Sharing a sentence is not in itself a finding about the gene and the disease.
COVID-19 (continued). "This systematic review and meta-analysis will summarize the association of IFNL4, ACE1, PKR, IFNG, MBL2 genetic polymorphisms, and severe COVID-19." (PMID 35623072, 2022). "A single-cell transcriptional study performed in PBMCs of COVID-19 patients further suggests the involvement of IFNα and IFNγ in promoting severe disease via activation of STAT1/IRF3 in CD4+ and CD8+ T cells, naive T cells, and DCs." (PMID 35244141, 2022). "Plasma levels of TNFα, IL-2, IL-6, IL-8, IL-10 (p < 0.001), IFNγ (p < 0.01), and GM-CSF (p < 0.05) were higher in COVID-19 patients compared to in HCs." (PMID 35625671, 2022). "In the present study, we detected significantly higher serum levels of measured cytokines, chemokines, and inflammatory proteins (IP-10, CRP, IFNγ, IL-10, IL-13, IL-17α, IL-23, and IL-6) in COVID-19 patients than in controls." (PMID 36554094, 2022). "So far, only two studies have evaluated the prognostic role of in vitro IFNγ production in COVID-19 patients." (PMID 36016305, 2022). "Among these secreted factors, only IFNγ responses correlated with disease severity and showed significantly higher magnitudes in mild compared to severe COVID-19 (p = 0.010)." (PMID 35806161, 2022). "Gene expression of IFNG was increased by 70% in PBCs of COVID-19 patients compared to control subjects (Student’s t test), and the increase was more marked in mild and critical patients than in severe patients (one-way ANOVA, post-hoc analysis)." (PMID 36009555, 2022). "Though other cytokines and chemokines must be involved, these results underline the therapeutic potential of IFNγ and TNF blockade as COVID-19 treatment." (PMID 35023830, 2022). "Complicated cases of COVID-19 exhibit higher levels of proinflammatory cytokines, such as IL6 and IFNG, making them more susceptible to neurological complications." (PMID 35794518, 2022). "Single nucleus transcriptional analyses of brain cells in patients who had died of COVID-19 revealed that astrocytes indeed acquire a specific transcriptional profile characterized by an up-regulation of interferon-gamma signaling." (PMID 35785352, 2022). "Study has been shown that an enhanced frequency of GM-CSF/IFNG replicating T cells was found in the blood of COVID-19 patients and appeared to correlate with disease activity." (PMID 36506032, 2022). "In spite of potential chronic activation in HD, our correlational evidence suggests an intact IFNγ/TNFα-IDO-Kyn axis sensitive to COVID-19." (PMID 36430566, 2022). "Serum levels of IP-10, CRP, IL-10, IFNγ, IL-13, IL-17α, IL-23, IL-6 were particularly upregulated in COVID-19 patients compared to controls." (PMID 36554094, 2022). "Studies report either robust activation of the T-cells in critical cases with a high percentage of IFN-γ-producing CTL cells or severe COVID-19 as an immunosuppressive phenotype, exemplified by profound declines in IFNγ- and TNF-producing T cells." (PMID 35401519, 2022). "We also observed significantly increased percentages of S-specific CD8 T-cells expressing IFNγ in unvaccinated oncologic patients with previous COVID-19 compared to their healthy counterpart group." (PMID 36139625, 2022). "On the other hand, the IRF7 (Interferon regulatory factor 7) and IFNG (Interferon Gamma) were found to be downregulated in severe COVID-19 patients." (PMID 35422859, 2022). "Serum IP-10, MCP-1, CRP, IFNγ, IL-10, IL-13, IL-17α, IL-23, and IL-6 were significantly higher in COVID-19 patients compared to controls." (PMID 36554094, 2022). "NK cells also react to and generate cytokines such as IL-12 and IL-2, as well as IFNg, TNFa, and IL-6, with all these cytokines being amplified in the COVID-19 cytokine storm." (PMID 35669157, 2022). "This cytokine pattern is thought to be beneficial, because patients with severe COVID-19 are usually characterized by decreased IFNγ levels and a shift to a more Th2 profile." (PMID 35062730, 2022).
COVID-19 (continued). "On the other hand, in aged individuals who are prone to a severe course of COVID-19, the levels of IFNγ-producing virus-specific cells decreased, which implied the importance of Th1 cells in the development of protective immune response." (PMID 35632823, 2022). "When analyzing the subset composition of Th17 cells in COVID-19, a decreased proportion of Th17.1 and Th1 lymphocytes capable of IFNγ production was noted, as well as a slight decrease in circulating Tregs." (PMID 35632823, 2022). "This increased activity of cytotoxic population was also observed in NKT cells, which expression of IFNγ was increased 4.8-fold (p = 0.0079), in comparison with healthy individuals who had mild COVID-19." (PMID 35456230, 2022). "Elevated IFNG levels have been found in COVID-19 patients, and elevated IFNG levels are thought to exacerbate cytokine storms." (PMID 36506032, 2022). "After PWM stimulation, COVID-19 patients showed a reduced release of IFNγ, while IL-2 levels were found similar and TNF levels were increased compared to healthy controls." (PMID 36109525, 2022). "Recombinant IFNγ and IFNα2b are frequently used to treat cancer either alone or in combination with other therapies whenever there is a coinfection with COVID-19." (PMID 36299504, 2022). "This cytokine pattern is thought to be beneficial because patients with severe COVID-19 are usually characterized by decreased IFNγ levels and a shift to a more pronounced Th2 profile." (PMID 36016181, 2022). "Six hub genes (FCGR3A, CD69, IFNG, CCR7, CCL5, and CCL4) were closely associated with COVID-19 and HF." (PMID 36420258, 2022). "The latest laboratory findings from Wuhan patients also showed that mild COVID-19 patients had elevated levels of IL-1B, IFNγ, CXCL10, and CCL2, whereas in severe cases, G-CSF, CXCL10, CCL2, and CCL3 were elevated." (PMID 34441862, 2021). "MAIT cells both from COVID-19 patients and from healthy controls significantly upregulated IFNγ expression following E. coli stimulation." (PMID 33546489, 2021). "Accordingly, some ongoing RCTs are studying glucocorticoids and blockage of IL-1, IL-6, and IFNγ in COVID-19." (PMID 33495742, 2021). "The high surge of IL6, IL1b, IFNγ, C-reactive protein, and TNF-α senescence leads to lower airway and lung injury and increased risk for COVID-19 in elderly patients." (PMID 33815889, 2021). "First, many of the same cytokines that are elevated with high-dose IL-10 administration in the studies discussed above (e.g. IL-4, IL-7, IL-18, IFNγ, TNFα) are also elevated in severe COVID-19 cases in conjunction with elevated IL-10 levels." (PMID 34234779, 2021). "The main difference in post COVID-19 versus unexposed HC were observed in IFNγ+TNFα+IL-2+ tp activated CD4+ T cells." (PMID 34322120, 2021). "Initially, we observed that SARS-CoV-2-specific memory CD4+ and CD8+ secreted low levels of IFNγ and only a small proportion of the T cells from COVID-19 patients gained multifunctionality (IFNγ and TNF dual expression)." (PMID 33741972, 2021). "Emapalumab (Swedish Orphan Biovitrum) is a human IgG1 raised against interferon gamma, approved for treatment of primary hemophagocytic lymphohistiocytosis, and evaluated in a Phase 2/3 in patients with COVID-19 (NCT04324021)." (PMID 33668613, 2021). "The frequency of IFNγ-producing Th cells was found to be decreased among the total Th cells in patients with severe COVID-19 compared to those in patients with moderate infection." (PMID 34696395, 2021). "Recent published studies have reported that elevated inflammatory cytokine (such as TNFα, IL-1β, IL-6, IL-10, IL-17, IL-18, and IFNγ) levels were seen in active COVID-19 cases compared to healthy donors." (PMID 34348897, 2021). "For example, synergism of interferon-gamma and tumor necrosis factor-mediated signaling can perpetuate a COVID-19-induced cytokine storm by stimulating programmed cell death (apoptosis and necroptosis) and increasing mortality." (PMID 34975885, 2021).
COVID-19 (continued). "We show that hypercytokinemia in COVID-19 differs from the interferon-gamma-driven cytokine storm in macrophage activation syndrome, and is more pronounced in critical versus mild-moderate COVID-19." (PMID 34226537, 2021). "Recently, the global COVID-19 pandemic has brought attention to the devastating effects of cytokine storms, with one study finding that TNFα and IFNγ synergize to trigger inflammatory cell death and increased mortality in SARS-CoV-2 infection." (PMID 33617447, 2021). "PIMS-TS children had significantly elevated levels of cytokines, IFNγ, IL-2, TNFα, IL-1α, IFNα, IFNβ, IL-6, IL-17A, GM-CSF, IL-10, IL-33 and IL-Ra in comparison to COVID-19, seropositive and control children." (PMID 33813138, 2021). "Of note, concentrations of circulating IL-7 and IFNγ, which are increased in severe COVID-19, are similar in men and women." (PMID 34434199, 2021). "TNFα and IFNγ are known to particularly drive COVID-19 disease severity and in addition, IL-6, IL-1β and IL-12 have been consistently implicated in severe disease." (PMID 33813138, 2021). "CD4+ T lymphocytes producing IFN-γ were the principal phenotype for memory T cells after virus exposure in COVID-19 and can be the key for vaccine development and protective evaluation, as well as the IFNG expression with antiviral genes." (PMID 34571855, 2021). "Given only established genetic predictors of interleukin-18 exist, we primarily assessed the role of interleukin-18 in COVID-19 by severity, and secondarily the role of interleukin-12, interleukin-23 and IFNγ." (PMID 34911594, 2021). "Patients with mild COVID-19 symptoms showed significantly higher amounts of IFNγ-producing cells compared to individuals with severe or critical diseases." (PMID 34194438, 2021). "Our data clearly demonstrates a significantly stronger induction of SARS-CoV-2 specific CD8+ T lymphocytes and higher IFNγ production in patients with mild compared to patients with severe or critical COVID-19." (PMID 34194438, 2021). "While we did not observe any significant difference in the levels of IFNα and IFNγ in our study group, higher IL-21 levels in severe COVID-19 patients suggests the existence of a hyper inflammatory condition in this group." (PMID 34199203, 2021). "COVID-19 children had elevated levels of IFNγ, IL-2, TNFα, IL-1α, IFNα, IFNβ, IL-6, IL-17A and IL-10 in comparison to seropositive and/or control children." (PMID 33813138, 2021). "Type II IFN (IFNγ) was only significantly decreased in PBMCs from P2 compared to HC, but increased in P1 and P3 compared to COVID-19 patients." (PMID 34531865, 2021). "IFNG expression was detected in the T cells from bronchoalveolar lavage fluid of patients with COVID-19." (PMID 34869070, 2021). "Our data demonstrated that after being induced by Prot_S, Calu-3 cells showed the upregulation of TNFα, IL6, IL1β, and IFNγ, which is in line with the clinical situation of patients with COVID-19." (PMID 34074129, 2021). "Oddly, however, the release of cytokines interferon alpha (IFNα) and interferon gamma (IFNγ) are severely impaired in severe COVID-19." (PMID 33672738, 2021). "Further, the level of circulating Th cells capable of producing IL-6, GM-CSF, and IFNγ was reported to be significantly increased in patients with COVID-19, especially in patients with severe infection." (PMID 34696395, 2021). "To evaluate the quality of SARS-CoV-2-specific memory T cells, we measured the MFI of IFNγ by intracellular staining in the memory T cells from COVID-19 patients and close contacts." (PMID 33741972, 2021). "Lymphocyte count was negatively associated with IFNγ, IL-2, TNFα, IL-1α, IFNβ, IL-6, IL-17A, IL-10, CXCL-10 and VEGF in children with PIMS-TS and COVID-19." (PMID 33813138, 2021). "IFNg serum levels were found to be decreased in COVID-19 compared with both macrophage activation syndrome (MAS) and secondary hemophagocytic lymphohistiocytosis (sHLH), in which cytokine storm is seen." (PMID 34836309, 2021).
COVID-19 (continued). "CRP was positively associated with IFNγ, IL-2, TNFα IL-1α IFNβ IL-6 IL-17A IL-10, CXCL-10 and VEGF in children with PIMS-TS and COVID-19." (PMID 33813138, 2021). "Disease severity in COVID-19 correlates with the detection of various cytokines and chemokines including IFNγ." (PMID 33438988, 2021). "MIS-A patient PBMC responses to SARS-CoV-2 were largely similar to those of PBMCs from ICU patients with severe COVID-19, however IFNγ, TNFα; and IL-1β responses tended to be higher in MIS-A PBMCs although not significantly across all cases." (PMID 34531865, 2021). "Of note, among our cohort of severe COVID-19 patients, those with higher levels of circulating IFNγ were recruited between 5 and 14 days from clinical onset." (PMID 34858405, 2021). "The specific IFNγ-production by CD8+ T lymphocytes seen here suggests that the AstraZeneca COVID-19 vaccine was effective in this IBD case promoting activation of the antiviral defense." (PMID 34834950, 2021). "By IFNγ ELISPOT analysis, it was revealed that convalescent COVID-19 patients had significantly increased levels of IFNγ-secreting T cells when compared with healthy donors." (PMID 32808850, 2020). "In diseases characterized by a deregulated, massive secretion of pro-inflammatory cytokines (the so-called cytokine storm), such as severe COVID-19, one of the key cytokines involved in pathogenesis is interferon-gamma (IFN-gamma)." (PMID 33553231, 2020). "As confirmed also by multivariable analysis, stimulated IFNγ levels are an independent predictor of complications in patients with COVID-19 [p = 0.0349 OR = 0.98 (0.962; 0.999)]." (PMID 33585507, 2020). "The lowest levels of IFNγ in early illness were seen in those who succumbed to their illness due to COVID-19." (PMID 33199778, 2020). "Lower frequencies of IFNγ producing CD4+ T cells in severe COVID-19 were confirmed in another study." (PMID 33133083, 2020). "These cells represent a potentially underappreciated source of both IFNγ and proinflammatory cytokines, such as TNFα, and contributors of disease progression in COVID-19." (PMID 32431755, 2020). "The involvement of such gene signatures emphasizes the link between innate immune response and effects of COVID-19 on interferon gamma signaling." (PMID 33138195, 2020). "Those who developed severe pneumonia in COVID-19 had high levels of many inflammatory cytokines and chemokines but low IFNγ levels." (PMID 33199778, 2020). "In vitro treatment with type IFNα restored type IFNγ secretion in COVID-19 patients while the secretion of pro-inflammatory cytokines IL6 and IL1β remained stable or decreased, respectively." (PMID 33585507, 2020). "It was first reported that several pro-inflammatory cytokines and chemokines, including IL-2, IL-7, IL-10, CXCL10 (IP-10), CXCL8, CCL2 (MCP1), TNFα, and IFNγ were higher in the plasma of COVID-19 patients as compared to healthy controls." (PMID 33363221, 2020). "In a study published in the Lancet, COVID-19 patients exhibit increased plasma levels of cytokines and chemokines, such as IFNγ, CXCL10, IL-1β, and TNFα." (PMID 32431755, 2020). "Results are explorative but indicate that DPSCs can down-regulate the production of cytokines by activated PBMCs, e.g., TNFα, IFNγ, IL-10, and IL-17A, which are up-regulated in COVID-19 patients." (PMID 33634100, 2020). "Pathogenic Th1 CD4+ T cells co-expressing IFNγ and GM-CSF were found only in the ICU patients indicating that these cells play an important role in the hyperinflammatory response of COVID-19." (PMID 33042116, 2020). "In contrast, patients with COVID-19 demonstrated activation of both Th1 and Th2 immunity, culminating inexpression of IFNγ, IL-1β, IL-4, and IL-10." (PMID 32742855, 2020). "In contrast, IFNγ production was reduced and IL-17 production enhanced in COVID-19 patients, indicating polarization toward a Th17 response." (PMID 33377122, 2020).
COVID-19 (continued). "Impaired cellular functionality in CD4+ and CD8+ T cells has been observed in severe COVID-19 cases along with generally lower interferon γ (IFNγ) and tumor necrosis factor α (TNF-α) production." (PMID 33362779, 2020). "The majority of acute and convalescent COVID-19 samples had measurable IFNγ+ CD8+ T cell responses by both ICS and secreted cytokines." (PMID 33010815, 2020). "For example, Coronavirus is more highly associated with Interferon-gamma than SARS, H5N1 or COVID-19; while Interferon-beta is less associated with SARS-related publications than Coronavirus- or H5N1-related publications." (PMID 32746922, 2020). "IFNγ, a Th1 molecule, was fourfold higher in COVID-19 patients as compared to controls despite the increased presence of markers of exhaustion and senescence and a skewing of cells toward TH17 phenotype." (PMID 33042116, 2020). "Clinical manifestations and atypical radiographic features of COVID-19 led to the diagnosis of TB through positive interferon-gamma release assay and culture results." (PMID 32667283, 2020). "However, GSEA on DEGs per cell state identified upregulated gene sets related to IFNγ signaling in LYVE1hiMHCIIlo, LYVE1loMHCIIhi and proliferating macrophages as well as in cDC2 from Post-COVID-19 patients." (PMID 39994453, 2025). "The results revealed that polymorphisms in the IL6, IL6R, IL1α, IL1R, IFNγ, TNFα, CRP, VDR, VDBP, and ACE2 genes are the most significant genetic factors influencing COVID-19 prognosis, particularly in terms of the risks of COVID-19 pneumonia, mortality, rehospitalization, and associated mortality." (PMID 40869297, 2025). "Our results highlighted an important role of IFNG expressed in lymphoid cells of post-COVID-19 heart tissue, reflected in ISG expression patterns in multiple cell types and states, and identified upregulated IL16 and IL18 expression as hallmarks of post-vaccination myocardial inflammation." (PMID 39994453, 2025). "IFNG plays a critical role in the immune response to SARS-CoV-2, the virus causing COVID-19." (PMID 40919176, 2025). "Post-COVID-19 patients additionally exhibited a distinct IFNγ response gene signature in ECs." (PMID 39994453, 2025). "Biological analysis revealed significant associations between certain PACS symptoms and biomarkers of viral activation (IFNγ, IP-10), COVID-19 severity (CD163) and vascular activation (VCAM-1, ICAM-1), mainly in subjects whose symptoms had lasted less than a year." (PMID 40449327, 2025). "Similarly, S- and N-peptide responsive CD4+ T cells, with a robust IFNγ response, were detected in PBMCs of COVID-19 convalescent patients." (PMID 41306976, 2025). "The observed maturation of different populations of immune cells may be the consequence of the elevated levels of IFNγ in the serum of COVID-19 patients." (PMID 41226415, 2025). "At the other end of the spectrum, optimal vitamin D levels could contribute to the reduction of inflammatory reactions mediated by interleukin-6 (IL-6) and interferon gamma (IFNγ), which are predictors of a poor prognosis in severe cases of COVID-19." (PMID 40427060, 2025). "We analyzed the frequencies of the two polymorphisms in the control groups (CG: TNF -308G/A, n = 497; IFNG +874T/A, n = 397), a group of patients with COVID-19 (CoV, n = 222) and among the subgroups of patients with nonsevere (n = 150) and severe (n = 72) COVID-19." (PMID 38675991, 2024). "In the present study, common clinical symptoms of COVID-19 such as fever and ageusia were associated with positive IFNγ responses in seropositive individuals but not in seronegative individuals." (PMID 38686954, 2024). "The detection of certain biomarkers in this study, mainly IL-17 and IFNγ, distinguish MISC_A from other COVID-19 patients and could assist in various clinical applications and treatment options." (PMID 39594853, 2024).